TGFB1 (transforming growth factor beta 1)
Diseases named in the same sentence as TGFB1 in open-access papers (continued):
Sharing a sentence is not in itself a finding about the gene and the disease.
tumor (continued). "Interestingly, the results demonstrated that, with the exception of TGFB1, the DNA methylation levels of the CpG sites in the other five biomarker candidates in tumor tissues were significantly lower in HNSCC tissues." (PMID 36425786, 2022). "In this study, we found that TGFB1 was significantly upregulated in tumor tissues and highly correlated with OS development, indicating that TGFB1 could play a stimulatory role in tumorigenesis and metastasis in OS." (PMID 35593122, 2022). "Furthermore, tumor-associated macrophages can express a variety of cytokines, including TGFβ1, that stimulate tumor cell proliferation and survival." (PMID 35804870, 2022). "Moreover, in this study, RSV was able to increase the levels of tumor-suppressor microRNA targeting TGFβ1 transcripts, the miR-663, and to decrease the transcriptional activity of SMADs as the main effectors of the canonical TGFβ pathway." (PMID 35327559, 2022). "Besides, the key regulatory factor of myofibroblast (transforming growth factor beta 1 [TGFβ1]) has substantial influence on HS formation, which also has long been recognized as a key molecule implied in tumor development and progression." (PMID 36169254, 2022). "Interestingly, CD105pos and CD105neg subpopulations of normal pancreatic fibroblasts were also isolated which retained their CD105 status even after co-culture with a tumour cell-conditioned medium or with fibroblast-modulating signals (TGFβ1, Il1a and IFNγ)." (PMID 36358721, 2022). "It was also observed that HER2 activated the tumor-progression effect by TGFβ1." (PMID 35650563, 2022). "Tumor-associated macrophages (TAM), myeloid-derived suppressor cells (MDSCs), and regulatory T cells (Treg) which are present in the tumor microenvironment are responsible for the production of TGFβ1 which orchestrates tumor metastasis and EMT-permissive tumor microenvironment." (PMID 34220337, 2021). "In addition, tumor biomarkers such as expression of NOTCH1, tumor hypoxia, and genetic variants in genes such as TGFβ1, COX7A1, and TBX5 have also been shown to be associated with prognosis in HPV-related HN cancer." (PMID 34830844, 2021). "We observed that CCDC137 was significantly correlated with TGFB1 expression in most tumor types including UVM and LGG, which may indicate the potential mechanism of CCDC137 influencing infiltration of TAMs/CAFs." (PMID 34055889, 2021). "Since CAFs secreted higher TGFβ1 level than tumor cells or NAFs and TGFβ1 increased CAFs’ migration, we inferred one reason for this was that SCC/CAF secreted higher amount of TGFβ1 which increased fibroblast activation, and this enabled CAFs to establish in the tumor core." (PMID 34527666, 2021). "Current hypotheses on the effects of TGFβ1 on tumor development suggest that increased amounts of this cytokine activity may suppress the early stages of tumor development but promote the invasiveness, metastasis, and angiogenesis of advanced tumors." (PMID 34722128, 2021). "Similarly, in the case of uterine carcinosarcoma, relative TGFβ1 transcript level has shown a trend towards higher expression in patients with tumor recurrence." (PMID 34501347, 2021). "Specifically, inhibition of TGFβ might prevent c-Myc induced cell death, leading to accelerated tumor development, whereas overexpression of TGFβ1 might facilitate apoptosis, resulting in the delay of HCC formation." (PMID 33608500, 2021). "We hypothesized that TGFβ1 was correlated with poor prognosis, might act as an indicator for tumor immune microenvironment of CC, and potential immune therapies targeting TGFβ1 might provide new hope to colon patients." (PMID 33995472, 2021).
tumor (continued). "Indeed, when c-MYC activation/overexpression was coupled to overexpression of the anti-apoptotic gene Mcl-1, the pro-apoptotic function of TGFβ1 was bypassed, ultimately resulting in tumor formation." (PMID 33608500, 2021). "Moreover, TIPE2 promoted T cell activation to exert an anti-tumor effect possibly through activation of DCs in a TGFβ1 dependent manner." (PMID 34249724, 2021). "In addition, the low TGFβ1 level in CAFs appeared to enhanced tumor cell development, radioresistance, and anti-tumor immunity, calling for different treatments." (PMID 34095135, 2021). "However, the ability of aTGFβ1 to interfere with the growth-arresting and, hence, tumor-suppressive function of (exogenous) TGFβ1 also makes it a potential oncogenic driver in early PDAC and BC development." (PMID 33802809, 2021). "As can be seen in these photographs, the glandular epithelial cells in PA and RPA, and the cancer cells in CXPA were mainly positively stained with SCF, whereas the fibroblast-like spindle cells were the main cellular source of TGFβ1 in all three tumor types examined." (PMID 34884420, 2021). "However, the effect of TGFβ1 in CAFs on tumor immunity was inconsistent with the prognosis of clinical patients." (PMID 34095135, 2021). "Furthermore, M2 polarization is characterized by the expression of surface CD163 and CD204, expression of intracellular STAT-3 and the production of arginase, IL-10, and transforming growth factor beta 1 (TGF-β1), supporting tumor invasion and angiogenesis." (PMID 33917013, 2021). "The enhancement of EMT might also involved in progression of tumor, CAFs could secrete TGFβ1 to promote EMT, and then promoted tumor invasion and metastasis." (PMID 34735373, 2021). "However, TGFβ1 secreted by tumor cells inhibits iCAF formation by antagonizing IL1 signaling activity and prevents myCAF conversion to iCAF by blocking the JAK/STAT pathway." (PMID 34218518, 2021). "However, TVT employs an immuno-suppressive mechanism largely reliant on the secretion of TGFβ1 by tumor cells." (PMID 34869014, 2021). "Therefore, the aim of this study was to verify the genotype frequencies of TGFB1 rs1800468, 1800469, 1800470, and 1800471, and their haplotype structures in WT patients and neoplasia-free controls in a Brazilian population." (PMID 34722128, 2021). "The expression of TGFβ1 might be an indicator for the tumor immune microenvironment of CC and serve as a prognostic factor." (PMID 33995472, 2021). "These incongruous reports suggest that the functions of TGFβ1 are complicated and may be specific for different tumor types." (PMID 34095135, 2021). "Firstly, tumour cells can produce inhibitory cytokines such as transforming growth factor beta 1 (TGF-β1) in the tumour microenvironment, and TGF-β1 protein is found to be elevated in the serum of dogs with metastatic oral melanoma relative to healthy control dogs." (PMID 34822659, 2021). "Finally, both palladin isoforms are needed for enabling robust canonical TGFβ1 signaling and for CAFs to generate d-ECMs with pro-tumor functions." (PMID 33589694, 2021). "Our current study demonstrated that CAFs could produce TGFβ1 at higher levels than tumor epithelial cells, and TGFβ signaling plays a major role in CSC expansion in a foreign (metastatic) microenvironment." (PMID 34527666, 2021). "TGFβ1-low levels promoted tumor cell growth and radiotherapy sensitivity in vivo and in vitro." (PMID 34095135, 2021). "Interestingly, in non-tumour Inv mice, similar treatment instead led to a significant reduction of Tgfb1 expression." (PMID 34511060, 2021). "We observed that FUCA2 was significantly correlated with TGFB1 and IL-10 expression in most tumor types including, which may indicate the potential mechanism of FUCA2 influencing infiltration of TAMs." (PMID 34745134, 2021). "Nonetheless, the number of tumor nodules was limited in c-Myc/TGFβ1 mice." (PMID 33608500, 2021).
tumor (continued). "However, higher TGFB1 mRNA expression, tumor region, age stage, gender stage, and primary site progression were not related to overall survival." (PMID 35047627, 2021). "Moreover, high levels of TGFB1/2 and ZEB1 were significantly associated with lymphatic invasion and advanced tumor stage." (PMID 34706749, 2021). "Mice with overexpression of TGFB1 in the mammary glands had greater tumor invasion and metastasis." (PMID 34771552, 2021). "We confirmed that TGFβ1 acted on tumor cells, causing a series of changes: upregulation of LAMC1; phosphorylation of NF‐κB; secretion of CXCL1; phosphorylation of STAT3 in CAF; and finally, the induction of the formation of iCAF, that is, tumor‐promoting CAF." (PMID 34218518, 2021). "The current results suggest a direct link between TGFβ1 and tumor radiosensitivity." (PMID 34095135, 2021). "TGFβ1, as one of the most important factors of modulating the function of DCs in tumor microenvironment, has been proved that could induce DCs tolerance directly, or increase the expression of PD-L1 on DCs in a STAT3 dependent manner." (PMID 34249724, 2021). "These pro-tumorigenic myeloid cells can synthesize TGFβ1 to promote EMT of surrounding tumor cells." (PMID 33946986, 2021). "In addition, gene expression in the primary tumor (T-TIS) was higher compared to control (N-TIS) for most genes (TGFβ1, COL1A1, COL3A1, ITGAV, ITGAX) (matched samples)." (PMID 33718208, 2021). "Regarding HCC cell levels, TGFB1 was a potent growth inhibitor and induces apoptosis in these cells, so it is regarded as a tumor-suppressive cytokine.Therefore, further studies are needed to validate and establish the specific molecular mechanisms by which curcumin regulates HCC cells." (PMID 34754622, 2021). "Moreover, in murine xenograft models, human tumor cell lines that ectopically express human TGFβ1 can elicit IL-11+ CAFs24." (PMID 33863879, 2021). "In addition, TGFβ1 was up-regulated in the tumor samples and significantly related with poor prognosis of CC patients." (PMID 33995472, 2021). "TGFβ1, 10 ng/ml, treatment increased not only the number but also the diameter of the BxPC-3 tumor spheres, and this effect could be reversed by the TGFβ1 receptor inhibitor SB431542 (10 μM)." (PMID 34849465, 2021). "The finding that aTGFβ1 impairs invasive activities induced by exogenous/rhTGFβ1 suggests an anti-oncogenic function in late-stage carcinomas when malignant progression is largely driven by high concentrations of stromal cell-derived TGFβ1 in the tumor microenvironment." (PMID 33802809, 2021). "The TGFB1 expression was significantly higher in the tumor tissue (p = 0.031)." (PMID 34804939, 2021). "Such agents, in combination with anti-TGFβ1 therapies, might block the recruitment of new fibroblasts into the growing tumor, helping to restrain the cancer and avoid new stroma activation." (PMID 34066976, 2021). "Subsequently, mice would be allowed to develop tumors, and TGFβ1 could be induced in tumor bearing mice via feeding the mice a doxycycline diet." (PMID 33608500, 2021). "METTL14 expression showed a negative association with TGFβ1, which is known to promote tumor immune tolerance by upregulating PD1 expression on T cells." (PMID 34221955, 2021). "In this environment tumor cells have been shown to interact with the PMCs via TGFβ signaling, wherein cancer cell derived TGFβ1, via TGFβ1 receptor interactions on the PMCs’ activates a RAC1/SMAD pathway, leading to increased fibronectin expression and a mesenchymal phenotype in the PMCs." (PMID 33590419, 2021). "In this study, increased levels of IL10, IL6 and TGFB1 correlated with an increased tumor burden." (PMID 33911154, 2021).
tumor (continued). "Transforming growth factor (TGFB1) was generally up-regulated in tumor cells, and could induce epithelial–mesenchymal transition and promote tumor cell growth, proliferation and invasion." (PMID 38650282, 2021). "Tumor-infiltrating monocytes and macrophages suppress the function of NK cells by repress interferons-γ (IFNγ), TNFα, and Ki-67 expression of NK cells through TGFβ1." (PMID 33406733, 2021). "Lung stromal cells isolated from obese tumor-naïve mice showed increased proliferation, contractility, and expression of extracellular matrix, inflammatory markers and transforming growth factor beta-1 (TGFβ1)." (PMID 33670906, 2021). "Importantly, TGFβ1 staining was significantly higher (p < 0.0001) in hepatocytes at the tumor-liver interface where the hepatocytes of the normal adjacent liver and cancer cells in the replacement HGP are in very close proximity." (PMID 34376784, 2021). "Furthermore, TGFβ1 and GM-CSF suppress chemotherapeutic effects by modulating the tumor microenvironment in pancreatic cancer." (PMID 33406733, 2021). "During tumor progression and concerning tumor immunity, the role of TGFβ1 is pivotal." (PMID 34095135, 2021). "TGFβ1 and its receptor are dysregulated by promoter methylation in several tumor types." (PMID 32397183, 2020). "What’s more, TGF-β promoted infiltration of immune cells and cancer-associated fibroblasts in the tumor microenvironments, and our present study showed that HSD17B6 could inhibit the expression of TGFB1." (PMID 32514254, 2020). "It has been suggested that Snail-1 expression, together with TGFβ1, is associated with lymph node metastasis in PTC and may be a potential biomarker of tumor diagnosis and prognosis in PTC." (PMID 32825554, 2020). "Hence, GLT treatment significantly inhibits TGFβ1 signaling, and along with CT increases survival and tumor doubling time in animals bearing UCS tumors." (PMID 33150300, 2020). "TGFβ1 is thought to be the primary isoform which is overexpressed in many tumor types and may promote tumor invasion and metastasis through multiple Smad-independent or non-canonical signaling pathways." (PMID 32825554, 2020). "Reduction of TGFB1 inhibits Treg cells in the tumor microenvironment." (PMID 33194642, 2020). "Furthermore, we showed here that loss of HSD17B6 affected the androgen biosynthesis and androgen signaling pathway, promoted tumor cell proliferation, migration, invasion, immune cell infiltration and immune evasion partially through TGFB1." (PMID 32514254, 2020). "Fluorescence microscopy (×100) showed that TNBC xenograft tumor zebrafish model could be established by inoculating TGFβ1‐treated MDA‐MB‐231 cells with CM‐DiI labeled into zebrafish." (PMID 32037729, 2020). "MMP-14 has been showed to be activated by TGFβ1, and then plays a complex role in tumor formation, angiogenesis and invasion through destruction and reconstruction of the basement membrane 67.TGFβ1 signaling promotes migration, progression and growth of the late carcinomas." (PMID 31956360, 2020). "UCA1 could be upregulated by TGFβ1 and promote tumor growth of HCC via influencing lactate production, glucose uptake and ATP production." (PMID 33292618, 2020). "Furthermore, cancer-associated fibroblasts (CAFs) are one of the most expressed cells in the tumor microenvironment, and the principal source of TGFβ1." (PMID 32766254, 2020). "Western blotting showed that compared with the EMT model group, FH could significantly increase E‐cadherin and reduce Snail2, ZEB2, TWIST1, and TGFβ1 protein expression in TNBC xenograft tumor zebrafish (P < .01.05)." (PMID 32037729, 2020). "The major cell type expressing MMP9 mRNA and protein were tumor‐infiltrating neutrophils, while Tgfb1 mRNA expression was mostly restricted to tumor‐infiltrating monocytes and Tgfb2, and Tgfb3 mRNA expression was mostly restricted to tumor epithelium and stroma." (PMID 31793740, 2020).
tumor (continued). "Besides being secreted by tumour educated‐stromal cells and carcinoma cells, transforming growth factor‐beta 1 (TGF‐β1) can also be produced by MSCs in the tumour environment." (PMID 32965772, 2020). "Using a TGFB1-inducible SMAD- responsive promoter for MSC-mediated NIS gene therapy in combination with external beam radiation dramatically increased the therapeutic efficacy of NIS gene therapy with complete tumor remission seen in a subset of mice." (PMID 32292510, 2020). "Thus, it is conceivable that the production of TGFβ1 by tumor cells is responsible for decorin downregulation in the neighboring fibroblasts." (PMID 32477937, 2020). "It indicated that TGFβ1‐treated MDA‐MB‐231 cells had a strong tumor formation ability and FH could significantly inhibit the growth of TNBC xenograft tumor in zebrafish." (PMID 32037729, 2020). "Based on our contention that RAC1B functions as a tumor suppressor, while autocrine TGFβ1 is considered a tumor promoter, we originally hypothesized that if RAC1B indeed targets TGFβ1 this interaction will be inhibitory." (PMID 33260366, 2020). "In conclusion, our results clearly suggest that targeting TGFβ1 using GLT may be exploited as an important therapeutic approach to reduce tumor growth, EMT and to overcome therapy resistance in UCS." (PMID 33150300, 2020). "CXCR7 silencing significantly represses cancer cell migration, invasion and epithelial-mesenchymal transition (EMT) induced by TGFβ1 in vitro, as well as sphere-forming capacity, stem-like properties, chemoresistance and TGFβ1-induced CSC tumor initiation in vivo." (PMID 33129326, 2020). "Thus, when tumor cells experience cellular stress and/or when TGFβ1 is abundant in the TME, pS134-GR self-perpetuates its own phosphorylation by inducing the expression of MAP3K5 which in turn activates p38 MAPK in cooperation with 14-3-3ζ." (PMID 32357907, 2020). "HSD17B6 may inhibit the expression of TGFB1 or other genes, and then inhibit tumor cell proliferation and invasion, immune cell infiltration and immune evasion." (PMID 32514254, 2020). "Development of TGFβ1-specific inhibitors that promote synergistic anti-tumor immune responses when combined with anti-PD-1, but lack cardiovascular pathologies have been identified and may lead to greater clinical utility." (PMID 32849557, 2020). "To further validate the expression of the metaplastic markers in human samples, we stained human PDAC and adjacent tumor sections and could detect TGFB1 and TFF1 in lesions and tumors." (PMID 32908137, 2020). "Other roles of TGFβ-1 include initiating epithelial-to-mesenchymal transition (EMT) and signalling endothelial-to-mesenchymal transition (EndMT), which in turn increases the cancer-associated fibroblast tumour load." (PMID 33139674, 2020). "Our data suggest that, in MF and P4 action, PGRMC1 may be the key LCT P4 receptor in the tumor-promoting action of TGFβ1." (PMID 33158280, 2020). "The levels of TGFβ1 in the different culture conditions were less dynamic, with only the co-culture with the primary tumor cell line exhibiting a significant difference between M1- and M2-activated macrophages, suggesting that TGFβ1 production increased slightly in the presence of M1." (PMID 31636296, 2019). "Finally, TGFβ is also central in the development of the tumour stroma because TGFβ1 also activates CAFs." (PMID 30704051, 2019). "The cellular dysfunction of TGFB1 may lead to tumor metastasis between the early and late stages of PTC." (PMID 31126066, 2019). "The expression of TGFB1 is increased in tumor cells compared with normal thyroid tissue, and it could be accepted by transforming growth factor beta receptor TGFBR3, which is a tumor suppressor protein." (PMID 31126066, 2019). "We further investigated whether TGFβ1-Smad signaling pathway was involved in the process that MSCs facilitated tumor growth and tumor interstitial microenvironment remodeling." (PMID 31528217, 2019).